FBRS (fibrosin)
Synonyms: FBS; FBS1; FLJ11618
Tractability: PROTAC: UniProt records ubiquitination sites on it; ubiquitination databases record sites on it.
Gene: Protein-coding gene on chromosome 16 (30,658,431 to 30,670,810, forward strand). Ensembl gene ENSG00000156860.
Subcellular location (Human Protein Atlas): Nucleoplasm
Genetic constraint (gnomAD): Loss-of-function variants: 14 observed, 61.78 expected, observed/expected ratio (o/e) 0.23, 90% interval 0.15 to 0.35. The synonymous counts are far from expectation, so gnomAD's model fits this gene poorly and the ratio says little. Missense variants: 1,234 observed, 1,055.5 expected, observed/expected ratio (o/e) 1.17, 90% interval 1.12 to 1.23. Synonymous variants: 611 observed, 447.05 expected, observed/expected ratio (o/e) 1.37, 90% interval 1.28 to 1.46.
Homologues: Orthologues: chimpanzee FBRS (99% identical), macaque FBRS (99% identical), dog FBRS (99% identical), pig FBRS (98% identical), rat Fbrs (96% identical), mouse Fbrs (95% identical), zebrafish fbrs (39% identical), tropical clawed frog fbrs (36% identical). Paralogues in human: AUTS2 (38% identical), FBRSL1 (29% identical).
Diseases named in the same sentence as FBRS in open-access papers:
FBRS is named in the same sentence as 2 diseases in open-access papers, as found by Europe PMC text mining. Sharing a sentence is not in itself a finding about the gene and the disease. The quoted sentences say what the papers report.
Hepatic fibrosis (1 paper, 2011). The presence of excessive fibrous connective tissue in the liver. "Serum levels of procollagen peptide (types III and IV), the P1 fragment of laminin, hyaluronic acid, fibrosin, TNF-aR-II and sICAM-1, tissue inhibitors of matrix metalloproteinases (TIMP)-1, and platelet-derived growth factors (PDFG)-BB may be elevated in patients with severe hepatic fibrosis." (PMID 21912706, 2011).
FBRS also shares sentences with these, for which no sentence is quoted: cardiovascular disease (1 paper).